ACTA1 (actin alpha 1, skeletal muscle)
Diseases named in the same sentence as ACTA1 in open-access papers (continued):
Sharing a sentence is not in itself a finding about the gene and the disease.
colorectal cancer (4 papers, 2019 to 2025). A primary or metastatic malignant neoplasm that affects the colon or rectum. "Recently, a bioinformatic analysis based on the aberrantly methylated differentially expressed genes and pathways in colorectal cancer (CRC) showed that ACTA1 may serve as an aberrant methylation‐based biomarker for precise diagnosis and treatment of CRC." (PMID 34313009, 2021). "Consistent with our observation, ACTA1 is also down-regulated in colorectal cancer." (PMID 30937621, 2019).
muscle disorders (4 papers, 2018 to 2024). "The pathological accumulation of actin thin filaments has also been reported in other myopathies and muscle disorders, such as progressive actin-accumulation myopathy caused by mutations in the Actin Alpha 1, Skeletal Muscle (ACTA1) gene." (PMID 39596480, 2024).
Skeletal myopathy (4 papers, 2023 to 2025). "In a patient, a VUS was identified in the cardiac troponin I (TNNI3) gene, and a variant meeting the AMG criteria for classification as likely pathogenic was also detected in the skeletal muscle α-actin (ACTA1) gene, which is primarily associated with skeletal myopathy." (PMID 40428316, 2025).
Myotonia (3 papers, 2018 to 2023). An involuntary and painless delay in the relaxation of skeletal muscle following contraction or electrical stimulation. "HSALR line LR41 features a lower transgene copy number, a lower ACTA1-CUGexp RNA abundance, deregulated alternative splicing to a lesser degree, less frequent myotonia (40% of mice examined by electromyography/EMG), and milder myopathy than HSALR line LR20b12,22." (PMID 37029100, 2023). "Intravenous injection of adeno-associated viruses (AAVs) carrying miRNA-based hairpin vectors that target ACTA1 transcripts reduced CUG-expanded RNAs by 60–95% in HSALR mice, in addition to reversing myotonia, muscle histopathology, and the formation of nuclear foci." (PMID 36362145, 2022).
actin accumulation myopathy (2 papers, 2008 to 2023). "Mutations in the skeletal muscle alpha actin gene (ACTA1) have been associated with various skeletal muscle diseases, including actin myopathy (accumulation of actin), NM, intranuclear rod myopathy and congenital fiber type disproportion (CFTD)." (PMID 19325803, 2008).
breast tumors (2 papers, 2012 to 2013). "We also compared methylation profiles for Tamoxifen resistant genes, and identified several hypermethylation genes in breast tumors, such as ACTA1, ISG15, PTK6 and SEPHS2." (PMID 23630576, 2013).
congenital muscular dystrophy (2 papers, 2024). A muscular dystrophy that is characterized by diminished muscle tone (hypotonia), progressive muscle weakness and degeneration (atrophy), abnormally fixed joints, spinal rigidity, and delays in reaching motor milestones such as sitting or standing unassisted. "Causative variants were found in nine patients with congenital muscular dystrophy in the ACTA1 gene (in one patient), GFPT1 (in one patient), PIGY (in two patients), POMT1 (in one patient), MCU1 (one patient), RYR1 (one patient), and TTN (one patient)." (PMID 37989827, 2024).
gynecological cancer (2 papers, 2017 to 2023). "Our approach has identified “actin (ACTA1)” and “myosin (MYH7)” combination with “MYBPC1” as the potential pathways causing promoter changes in gynecological cancers." (PMID 28927463, 2017). "Expression of ACTA1, MYH7, and MYBPC1 may be a potential promotor of gynecological cancer initiation or progression." (PMID 38248716, 2023).
myopia (2 papers, 2024 to 2025). "Because the retina is a neural tissue, the expression of numerous genes linked to cardiac muscle (MYBPC3, ACTC1, MYL3, MYH7, MYH7B) or to skeletal muscle (MYL1, SMYD1, TNNI2, MYH1B, ACTA1, TNNT3) presents a conundrum for explaining a mechanism for myopia progression." (PMID 39028695, 2024).
Obesity (2 papers, 2020 to 2024). Accumulation of substantial excess body fat. "In particular, the absence of TRIM28 in skeletal muscle, whether during development (MCK–cre) or postdevelopment (ACTA1–cre–ERT2), did not protect against HFD‐induced obesity or glucose intolerance." (PMID 39534556, 2024).
Sepsis (2 papers, 2024 to 2025). Sepsis is defined as life-threatening organ dysfunction caused by a dysregulated host response to infection. "Gene expression of Acta1 was unaltered upon sepsis, and only rAAV-shFermt2 treatment resulted in a minor decrease (P < 0.05)." (PMID 41385533, 2025).
autism (1 paper, 2016). Persistent deficits in social interaction and communication and interaction as well as a markedly restricted repertoire of activity and interest as well as repetitive patterns of behavior. "Three types of CvN unique genes were registered in the autism KB database: Cadm3 (cell adhesion molecule), Gpr83 (G protein-coupled receptor), and Acta1 (actin α1)." (PMID 27782041, 2016).
COVID-19 (1 paper, 2022). A disease caused by infection with severe acute respiratory syndrome coronavirus 2. "By taking the intersection of COVID-19/HCC genes and vitamin D-associated targets, we obtained seven overlapping genes (HMOX1, MB, TLR4, ALB, TTR, ACTA1 and RBP4) of vitamin D against COVID-19/HCC." (PMID 36275701, 2022). "Next, we further analyzed the possible binding of vitamin D with the seven COVID-19/HCC targets (HMOX1, MB, TLR4, ALB, TTR, ACTA1 and RBP4) identified previously and found that vitamin D only binds to MB and RBP4." (PMID 36275701, 2022). "Moreover, we identified seven possible pharmacological targets of vitamin D against COVID-19/HCC, including HMOX1, MB, TLR4, ALB, TTR, ACTA1 and RBP4." (PMID 36275701, 2022). "Further, we identified seven overlapping genes of vitamin D against HCC and COVID-19 using the network pharmacology approach, and the anti-COVID-19/HCC effects of vitamin D may be modulated by these molecules or genes, including HMOX1, MB, TLR4, ALB, TTR, ACTA1 and RBP4." (PMID 36275701, 2022).
degenerative myopia (1 paper, 2025). "ACTA1 (ENSP00000355645) is another specific gene predicted to be associated with degenerative myopia." (PMID 40110040, 2025).
diabetic cardiomyopathy (1 paper, 2024). Diabetic cardiomyopathy is a disorder of the heart muscle in people with diabetes. "Cluster 4 was enriched in genes of the ‘heart contraction’ (e.g., ACTC1, MYL3 and ACTA1) and ‘diabetic cardiomyopathy’ (e.g., TNNI3, MYH7 and GAS6)." (PMID 37766635, 2024).
dysplasia (1 paper, 2021). A usually neoplastic transformation of the cell, associated with altered architectural tissue patterns. "In mouse models, transgene overexpression of ACTC1 can alleviate muscle dysplasia diseases caused by a skeletal muscle α-actin (ACTA1) deficiency (ACTA1 disease)." (PMID 34944244, 2021).
GNE myopathy (1 paper, 2022). "Immunofluorescence was performed on two clones from Control1 and Control2, three clones from both GNE myopathy patient-derived lines and one clone from each Control3 and ACTA1 patient-derived lines." (PMID 36085325, 2022).
Lyme disease (1 paper, 2013). Lyme disease (named after the towns in the USA where the disease was first identified) is a bacterial infection caused by Borrelia burgdorferi. "To adapt the assay for diagnosis of Lyme disease in the patients, we spiked the same quantity of human DNA (350 ng genomic DNA or 105 ACTA1 copy number) with a ten-fold dilution of genomic DNA of B. burgdorferi." (PMID 24359556, 2013).
myofibrillar myopathy (1 paper, 2011). "The occurrence of ringbinden and features of myofibrillar myopathy in this mouse model of ACTA1 disease suggests that patients with these pathologies and no genetic explanation should be screened for ACTA1 mutations." (PMID 22174871, 2011).
oral squamous cell carcinoma (1 paper, 2024). "High expression of ACTA1 has been reported to be associated with shortened survival in oral squamous cell carcinoma." (PMID 39474352, 2024).
pancreatic ductal adenocarcinoma (1 paper, 2024). An infiltrating adenocarcinoma that arises from the epithelial cells of the pancreas. "In pancreatic ductal adenocarcinoma, ACTA1 expression is a feature of cancer-associated fibroblasts." (PMID 39474352, 2024). "In pancreatic ductal adenocarcinoma, ACTA1 expression is increased in stromal progenitor cells and fibroblast-like cells during carcinogenesis." (PMID 39474352, 2024).
recessive nemaline myopathy (1 paper, 2018). "However, upregulation of actc1a is sufficient to compensate for the loss of Actc1b mimicking the upregulation of ACTC1 in patients suffering from recessive nemaline myopathy caused by mutations in ACTA1." (PMID 29420541, 2018).
rhabdomyosarcoma (1 paper, 2021). A rare aggressive malignant mesenchymal neoplasm arising from skeletal muscle. "This inhibition of ACTA1 reporter activity was also observed in other Alveolar Rhabdomyosarcoma cell lines such as RH41 and RH4 cells." (PMID 33509264, 2021).
sarcoma (1 paper, 2025). A usually aggressive malignant neoplasm of the soft tissue or bone. "Both ACTA1 and ACTG1 were highly expressed in the PLMS and high-grade sarcoma groups, with expression more pronounced in the latter." (PMID 40868997, 2025).
vacuolar myopathy (1 paper, 2024). "However, an independent report has also linked an ACTA1 variant (p.Gly50Asp) with a rimmed vacuolar myopathy phenotype." (PMID 40225930, 2024).
Wilms tumor (1 paper, 2018). An embryonal neoplasm characterized by the presence of epithelial, mesenchymal, and blastema components. "We selected the ACTA1 gene which is 60‐fold up‐regulated in chemotherapy‐treated Wilms tumors to check whether ACTA1 protein expression levels correlate with gene expression levels." (PMID 29542868, 2018). "A protein preparation of an untreated Wilms tumor (ANS2) was analyzed as control and ACTA1 was undetectable (lane 7)." (PMID 29542868, 2018).
infection (66 papers, 2009 to 2026). The state of being infected such as from the introduction of a foreign agent such as serum, vaccine, antigenic substance or organism. "This cluster contained Acta1, encoding smooth muscle actin, as well as the actin crosslinking protein gene Actn3 and two myosin genes (Myo1h and Myh2), suggesting that both infection and Muc1 knockout disrupt the cytoskeleton." (PMID 32793510, 2020). "ACTA1, typically associated with skeletal muscle actin, and SGCG (Sarcoglycan Gamma), a component of the dystrophin–glycoprotein complex, are often linked to muscle integrity and may indicate cytoskeletal or structural alterations in the kidney post-infection." (PMID 40863220, 2025).
tumor (43 papers, 2012 to 2026). "We also reveal the potential of LL-37 in promoting tumor progression via the upregulation of cancer-related genes, such as ACTA1." (PMID 40004774, 2025). "An enrichment analysis with Toppgene revealed that over 10 of the 17 significantly upregulated genes in the tumours of the female mice were skeletal muscle genes such as Acta1, Actn3, Myh2, Myh4 and Des." (PMID 37840045, 2023). "Although ACTA1 transcript had been described in some RMS tumor samples, little work was paid attention to its protein expression and regulation in ARMS cells." (PMID 33509264, 2021). "ACTA1 transcript is significantly decreased in primary tumor compared to normal tissue (p = 1.25E-02), despite the low number of normal samples used." (PMID 33509264, 2021). "The potential role of ACTA1 to impair cell and tumor growth in ARMS was explored by in vitro and in vivo experiments." (PMID 33509264, 2021). "We also detected the expression differences of Ki67 in the tumor section with the higher level of Ki67 expression in tumors derived from RH30/vector control cells than those from RH30/ACTA1, suggesting the inhibitory effect of ACTA1on tumor growth." (PMID 33509264, 2021). "ACTA1 protein was analyzed in seven chemotherapy‐treated tumor samples and all are positive (lanes 2–5, lane 8 + 9); one tumor shows a low level (lane 6), confirming the gene expression data." (PMID 29542868, 2018). "HS-derived LL-37 stimulates tumor cells and increases the expression of ACTA1, which may be related to the poor prognosis of cSCC arising from HS." (PMID 40004774, 2025). "Notably, the expression of ACTA1 in tumor cells is higher in cSCC arising from HS compared to cSCC on the trunk without HS." (PMID 40004774, 2025). "Immunohistochemical experiments verified that high expression of ACTA1 was observed in tumor tissue samples undergoing PNI, and also the prognosis was worse in the ACTA1high group, which was largely consistent with previous bioinformatics predictions and reports by other scholars." (PMID 39474352, 2024). "So, we hypothesized that after tumor cells invaded nerve tissues, the invaded nerves could upregulate ACTA1 expression in tumor cells, leading to epithelial-mesenchymal transition of the cells, which promoted the invasion and metastasis of tumor cells." (PMID 39474352, 2024). "G3BP1, EIF2AK2, TRIM25, and ACTA1 were among the top-ranked proteins, and these were closely related to tumor proliferation, metastasis, and invasion, suggesting that seRNA-NPCM may play a crucial role in NPC tumorigenesis and development." (PMID 37479693, 2023). "Together, the data in the xenograft assay demonstrated that ACTA1 overexpression could suppress tumor growth in nude mice and thus may play a role in the tumorigenesis or progression of aRMS in vivo." (PMID 33509264, 2021). "The decreased ACTA1 in late-stage HCC may be caused by metabolic changes, and a number of results showed that over-expression of ACAT1 inhibited the proliferation and migration of tumor cells." (PMID 33865459, 2021). "Finally, the xenograft assay demonstrated that ACTA1 overexpression could suppress the tumor growth in the mouse model system used." (PMID 33509264, 2021). "Functionally, the overexpression of ACTA1 in RH30 ARMS cells reduced proliferation and migration in vitro and impaired tumor growth in vivo, supporting a tumor-suppressive role for ACTA1 in this context." (PMID 40508013, 2025). "Further, muscle markers TPM1/ACTA1 and the recently described HNSCC differentiation marker KRT17 correlate in the cell cultures and the original tumor tissue, indicating that our differentiation model faithfully reflects the differentiation behavior in human tumors." (PMID 39030166, 2024).
tumor (continued). "Cluster 1 comprises genes important for skeletal muscle (ACTA1) and muscle function (ACTN1) and includes a crucial gene (AKT1) known to regulate insulin signaling, cell survival, and tumor progression, as well as two chaperones: HSPA1A and HSPB1 (heat shock proteins (HSPs))." (PMID 36767649, 2023). "Although early study showed the existence of the alpha skeletal muscle actin gene (ACTA1) transcript in ARMS tumor samples, no more detailed work about ACTA1 in aRMS had been reported." (PMID 33509264, 2021). "In contrast, the tumor volume from RH30/ACTA1 cells was 969.41 ± 214.4 mm3, which suggested that the tumor growth may be suppressed by ACTA1 overexpression." (PMID 33509264, 2021). "Explanted allografts with TET2 KO MSCs were significantly smaller and histologically revealed significantly less cells with a CAF phenotype, on staining with aSMA (ACTA1), thus demonstrating less efficient CAF conversion and tumor supporting capabilities in vivo." (PMID 31663852, 2019). "Finally, we determined the potential role or function of ACTA1 in ARMS and the in vitro and xenograft assays showed that ACTA1 overexpression could suppress cell proliferation and tumor growth." (PMID 33509264, 2021). "Finally, we showed that ACTA1 overexpression in RH30 cells could inhibit cell proliferation and migration in vitro and impair tumor growth in vivo compared with the control groups." (PMID 33509264, 2021).
myopathy (36 papers, 2007 to 2026). A disease of the muscle in which the muscle fibers do not function properly. "The distal nebulin myopathy should be differentiated from other CMs with distal affection, such as those related to MYH7 or ACTA1 mutations, or other muscle diseases with anterior compartment involvement, such as myofibrillar myopathies." (PMID 32456280, 2020). "Both our overexpression and loss-of-function ACTA1 nemaline myopathy models show that actin imbalance in the skeletal muscle has pathogenic consequences." (PMID 25931053, 2015). "We previously generated mouse models of ACTA1 nemaline myopathy, with the D286G mutation and showed that the disease severity correlated with the percentage of mutant protein." (PMID 22174871, 2011). "Recently, a scapuloperoneal myopathy phenotype associated with ACTA1 has been reported." (PMID 41826152, 2026). "Correspondingly, canonical MEF2 target genes linked to myopathy and contractile function, including TNNT2, MYH7, ACTN2, and ACTA1, were also restored upon HDAC5 silencing." (PMID 41283336, 2025). "First, we reported 18 novel variations in 6 myopathy-causing genes, including RYR1, NEB, ACTA1, DNM2, TTN and TNNT1, and we described the clinical discrepancy between our patients and previous reports, especially in RYR1- and TNNT1- related myopathy." (PMID 35081925, 2022). "Our study verifies the existence of compensatory mechanisms, leading to a milder phenotype in ACTA1 recessive myopathy." (PMID 29420541, 2018). "ACTA1 (OMIM: 102610) is localized to the thin filament of the sarcomere, is involved in muscle contraction and when mutated, leads to severe forms of myopathy." (PMID 26815362, 2016). "We demonstrate that these subtypes can be differentiated immunologically in skeletal muscle biopsies from ACTA1 nemaline myopathy patients, potentially providing markers for disease severity and aiding in the identification of the causative mutation." (PMID 25931053, 2015). "We created a conditional transgenic zebrafish model for ACTA1 nemaline myopathy, Tg(ACTA1D286G-eGFP) that expresses human ACTA1D286G in skeletal muscles." (PMID 25931053, 2015). "We describe the generation of zebrafish ACTA1 nemaline myopathy models allowing us to investigate disease pathogenesis in vivo." (PMID 25931053, 2015). "Analysis of zebrafish and muscle biopsies from ACTA1 nemaline myopathy patients demonstrates that nemaline bodies also possess a different protein signature." (PMID 25931053, 2015). "Both SEPN1 and RYR1 were excluded, as were ACTA1 and TPM3, in which mutations cause congenital fiber type disproportion, a myopathy clinically similar to MmD." (PMID 22371254, 2012). "Various myopathies are known to be caused by this decoupling mechanism and result from variants in other skeletal muscle genes involved in the Ca2+-dependent contraction response, including TPM2, TPM3, and ACTA1." (PMID 32819427, 2020). "Interestingly, a zebrafish morpholino knock-down model of ACTA1 nemaline myopathy showed a milder phenotype because of a transcriptional upregulation of an actin paralogue, i.e. through genetic compensation." (PMID 31228046, 2019). "Most ACTA1 mutations are missense, dominant de novo mutations, with the majority of patients having a severe congenital myopathy phenotype and not surviving to one year of age." (PMID 22174871, 2011). "This patient, though, showed no signs of myopathy and had an apical wall thickness of 17 mm, making it uncertain whether the ACTA1 variant contributes to the cardiac phenotype." (PMID 40428316, 2025). "Finally, patients with large numbers of ringbinden-containing fibres and/or myofibrillar myopathy pathologies and no molecular explanation of their diseases should probably be tested for ACTA1 mutations." (PMID 22174871, 2011). "Both groups of TMX-treated ACTA1-MCM;FLExDUX4 mice rapidly displayed phenotypes consistent with a progressive myopathy." (PMID 29415061, 2018).